IGF1R (insulin like growth factor 1 receptor)
Diseases named in the same sentence as IGF1R in open-access papers (continued):
Sharing a sentence is not in itself a finding about the gene and the disease.
lung cancer (continued). "For instance, IGF-1R inhibitors have been investigated for lung cancer treatment, blocking the activation of the IGF-1R signaling pathway and inhibiting the proliferation and invasion of lung cancer cells." (PMID 38449844, 2024). "β-AR and NF-κB agonists were shown to increase IGF-1R phosphorylation, and treating mice with β-AR antagonists prevented the development of lung cancers." (PMID 39253534, 2024). "Clinical studies involving IGF-1R-targeted therapies in lung cancer patients have been conducted to evaluate the effectiveness of these therapies." (PMID 38540176, 2024). "Our findings emphasize the intricate mechanisms by which IGF-1R contributes to various aspects of lung cancer pathogenesis, including tumor proliferation, metastasis, EMT, stemness, and resistance to both chemotherapy and targeted therapies." (PMID 38540176, 2024). "To investigate IGF1R-related functional events, we searched the TCGA database of lung cancer to identify genes correlated with IGF1R mRNA expression." (PMID 38200153, 2024). "In this review article, we will discuss how tobacco smoke-specific carcinogens and IGF-1R signaling pathways are connected to lung cancer development, and how IGF-1R can serve as a potential target for lung cancer therapy." (PMID 38540176, 2024). "This review further highlights the challenges in using IGF-1R inhibitors as targeted therapy for lung cancer due to structural similarities with insulin receptors." (PMID 38540176, 2024). "The role of the IGF-1R signaling pathway is crucial in developing treatment resistance in lung cancer." (PMID 38540176, 2024). "The Insulin-like Growth Factor 1 Receptor (IGF-1R) is a receptor that plays a critical role in lung cancer development." (PMID 38540176, 2024). "Because many successful targeted anti-cancer therapies have relied heavily on the use of predictive biomarkers, more investigation into this area is crucial for determining the most effective application of IGF/IGF-1R inhibitors as a lung cancer therapy." (PMID 38540176, 2024). "In the present study, IGF1R expression was found to be upregulated in lung cancer patient tissues, and its protein levels were correlated with PRKCSH protein levels." (PMID 38200153, 2024). "It is well-established that the overexpression of IGF-1R and IGFs, as well as the deregulation of IGF-1R signaling pathways, are closely associated with the development of lung cancer." (PMID 38540176, 2024). "Several reports have shown that by activating IGF-1R, tobacco smoke-related carcinogens promote lung cancer and chemotherapy resistance." (PMID 38540176, 2024). "Inhibiting IGF-1R signalling has been studied as a potential treatment approach for lung cancer patients." (PMID 38905286, 2024). "As subsequent molecular profiling identified an ALK rearrangement, the study proposed the IGF-1R–IRS-1 signaling axis as a potential therapeutic focus in ALK+ lung cancer, providing insights for upcoming clinical trials." (PMID 38397899, 2024). "For example, in EGFR‐mutant lung cancer, IGF‐1R signal transduction required for the DT state is regulated via KDM5A demethylation." (PMID 37638338, 2023). "The expression of EGFR and IGF1R was also significantly higher in lung cancer tissues than in normal tissues." (PMID 37880793, 2023). "A549 cells and lung cancer tissues have been shown to be upregulated by estrogen through the IGF-1R signaling pathway." (PMID 37764733, 2023). "The activation of the insulin-like growth factor 1 receptor (IGF-1R) seems to be related to EGFR-TKI resistance as shown in in vitro studies on lung cancer cell lines resistant to gefitinib or erlotinib." (PMID 37376053, 2023). "The results showed that the mRNA expressions of AKT1, EGFR and IGF1R were upregulated in lung cancer tissues, while the expression of PI3KR1 was downregulated compared with normal lung tissues." (PMID 37533633, 2023).
lung cancer (continued). "There are a number of mechanisms that contribute to estrogen’s promotion of lung cancer, and ER and IGF-1R are promising targets for combination therapy against lung cancer." (PMID 37764733, 2023). "Overexpression of EGFR and IGF1R induces lung cancer cell proliferation, migration, invasion, drug resistance, stemness and tumor metastasis." (PMID 37880793, 2023). "THRIL can regulate the expression of IGF1R through miR-99a, thereby promoting the growth of lung cancer cells and inhibiting apoptosis." (PMID 37582734, 2023). "Many studies have confirmed that IGF1R is highly expressed in lung cancer tissue, and has important impacts on lung cancer." (PMID 37582734, 2023). "Another recent study demonstrated that enhanced IGFBP-7 expression promoted resistance to epidermal growth factor receptor tyrosine kinase inhibitors in lung cancer cells by mediating the IGF-1R pathway." (PMID 36902237, 2023). "Overexpression of IGF1R contributes to increased survival and inhibited apoptosis of lung cancer cells." (PMID 37582734, 2023). "A study revealed that FBLN3 restrained the stemness of lung cancer cells via the IGF1R/PI3K/AKT/GSK3β signaling pathway." (PMID 36385964, 2022). "The expression of IGF1-receptor (IGF1R), a tyrosine kinase receptor, is upregulated in most cancer types, including prostate, breast and lung cancer." (PMID 35574343, 2022). "Osimertinib-treated lung cancer patients were found to have increased IGF2 expression, and IGF2 autocrine-mediated IGF1R pathway activation is one of the causes of osimertinib resistance in lung cancer patients." (PMID 35684449, 2022). "Accordingly, IGF1R has been reported to contribute to the pathogenesis of lung cancer, as it is commonly overexpressed in NSCLC patients." (PMID 35688943, 2022). "Our previous study revealed that B7-H4 can be upregulated by IGF1R activation through the MEK/ERK1/2 signaling pathway in lung cancer." (PMID 35410218, 2022). "In contrast, IGF-1R downregulation sensitizes lung cancer cells to chemotherapy and radiation by inhibiting cell proliferation." (PMID 35205115, 2022). "miR-223 targets IGF-1R, a transmembrane receptor tyrosine kinase related to lung cancer oncogenesis, tumor growth, and cancer cell survival." (PMID 35205115, 2022). "In lung cancer cell lines insulin-like growth factor receptor (IGF-1R) inhibitor linsitinib treatment shortly decreased SRC activity but in a few hours SRC activity returned to an even higher level." (PMID 35392170, 2022). "Another meta-analysis of 2686 lung cancer patients examined common polymorphisms within the IGF axis, finding that certain patients had a predisposition to lung cancer due to genetic variations in IGF-I, IGF-II, IGF-1R, IGFBP-3, and IGFBP-5." (PMID 35198099, 2022). "IGF-1R is upregulated in multiple malignancies, including prostate, breast and lung cancer, where it is involved in tumor growth." (PMID 33535618, 2021). "Of note, FGFR overexpression and activation were identified as a mechanism of resistance to IGF-1R inhibitors and other targeted drugs in other tumor types, including in a rhabdomyosarcoma model and in lung cancer." (PMID 33916323, 2021). "Citrate can act on the IGF-1R-AKT-PTEN-eIF2a pathway to inhibit the growth of A549 lung cancer, and metabolic profile analysis has shown that it inhibits glycolysis and the tricarboxylic acid cycle in tumor cells both in vivo and in vitro." (PMID 34017341, 2021). "We have found that lung cancer cells react to GCs by transitioning to a dormant state accompanied by activation of IGF-1R survival signalling." (PMID 34272384, 2021).
lung cancer (continued). "Evidence of increased expression of insulin-like growth factor 2 (IGF2) and insulin-like growth factor receptor-1 (IGF-1R) in CAF accumulating-lung cancer tissues proved that CAFs promote chemoresistance through IGF2/IGF-1R signal." (PMID 34095111, 2021). "IGF1Rβ is highly activated in NSCLC patients with poor prognoses and low survival rates; thus, IGF1R is an attractive therapeutic target for lung cancer." (PMID 32971893, 2020). "The results showed that the expression of circ‐IGF1R in lung cancer cells (PC9, A549, Calu‐1, H1299, and H1975) was significantly lower than that in the control cell line, MRC‐5." (PMID 32107851, 2020). "Growing evidence indicates that IGF1/IGF1R is found highly expressing in multiple types of cancer such as colorectal cancer, non‐small cell lung cancer, prostate cancer, and gastrointestinal stromal tumors." (PMID 32851683, 2020). "Considering these issues, we chose the transient combination of the IGF-1R inhibitor with osimertinib, demonstrating a favorable efficacy and safety in the CDXs and PDX models of AXL-low-expressing EGFR-mutated lung cancer." (PMID 32929081, 2020). "In conclusion, we have shown that the low expression level of circ‐IGF1R is detected in lung cancer tissues and cell lines." (PMID 32107851, 2020). "The expression level of circ‐IGF1R was examined using quantitative reverse transcription‐polymerase chain reaction (qRT‐PCR) in five different lung cancer cell lines and 50 pairs of lung cancer and adjacent tissues." (PMID 32107851, 2020). "In lung cancer, IGF-1R signaling regulates CSC activities through the activation of different downstream cascades and cross-talk with the surrounding microenvironment." (PMID 33511137, 2020). "Our study also showed that the overexpression of circ‐IGF1R in lung cancer resulted in the downregulation of miR‐1270 expression and the inhibition of cell invasion and migration." (PMID 32107851, 2020). "The effect of overexpressing circ‐IGF1R on the transcriptome of whole lung cancer cells was explored in lung cancer cell lines using RNA‐seq." (PMID 32107851, 2020). "The overexpression of circ‐IGF1R significantly inhibited invasion and migration of lung cancer cells, and the opposite effect was observed when siRNA against circ‐IGF1R was used." (PMID 32107851, 2020). "The results suggested that circ‐IGF1R plays a part in the invasion and migration of lung cancer by regulating important miRNAs and genes." (PMID 32107851, 2020). "These proteins were downregulated after overexpressing circ‐IGF1R in lung cancer cells, while the expressions of related proteins were upregulated after interference with circ‐IGF1R expression using siRNA." (PMID 32107851, 2020). "We realized that the target gene of circ‐IGF1R is likely to be involved in the invasion and migration of lung cancer through the Wnt signaling pathway." (PMID 32107851, 2020). "To the best of our knowledge, we have identified for the first time that circ‐IGF1R can inhibit the Wnt/β‐catenin pathway through the circ‐IGF1R–miR‐1270–VANGL2 axis in lung cancer, thereby inhibiting cell invasion and migration." (PMID 32107851, 2020). "The overexpression of circ‐IGF1R significantly inhibited the invasion and migration of the lung cancer cells." (PMID 32107851, 2020). "To identify the expression of circ‐IGF1R in lung cancer cells, we first screened for circ‐IGF1R in six cell lines using qRT‐PCR." (PMID 32107851, 2020). "A recent investigation showed that the nuclear accumulation of IGF1R in lung cancer contributed to EGFR-TKIs resistance observed in vivo and in vitro." (PMID 30823937, 2019). "Inhibition or depletion of IGF-1R enhances the sensitivity of human cancer cells to IR and cytotoxic drugs in melanoma, prostate, and lung cancer." (PMID 31467485, 2019). "In this study, we found that IGFBP7 contributes to resistance to EGFR-TKIs and showed that enhanced IGFBP7 expression promoted resistance to EGFR-TKI in lung cancer cells by mediating the IGF-1R pathway." (PMID 30609749, 2019).
lung cancer (continued). "While enhanced IGFBP7 expression promoted resistance to EGFR-TKIs in lung cancer cells, IGF-1R activation has been reported to confer acquired resistance to EGFR-TKIs." (PMID 30609749, 2019). "The combination of IGF-1R antibody and radiation has been a challenge in lung cancer and head and neck cancer." (PMID 31467485, 2019). "A study conducted in the Chinese population showed that IGF-1R was highly expressed in type 2 diabetes patients with lung cancer." (PMID 31354621, 2019). "Activation of IGF-1 receptor (IGF-1R) signaling confers resistance to afatinib in EGFR T790M-mutant lung cancer cells." (PMID 30609749, 2019). "In NSCLC, it directly targets p85α, IGF1, and IGF-1R, resulting in a decrease of pAKT signaling and downstream pFoxo3a activity, thus preventing proliferation, and promoting in vitro and in vivo lung cancer apoptosis." (PMID 31847392, 2019). "In lung carcinoma, overexpression of IGF-1R induces the activation of AKT/MEKK3, and then promotes the response of NF-κB signaling to TNF-α." (PMID 31847392, 2019). "Knockdown of TESC suppressed CSC-like properties as well as STAT3 activation through inhibition of insulin-like growth factor 1 receptor (IGF1R), a major signaling pathway of lung cancer stem cells." (PMID 30013043, 2018). "One thousand nine hundred twenty-six patients with lung cancer were then recruited to study the association between differential expression of BCL2L1 and IGF1R and patient survival using Kaplan-Meier and Cox regression method." (PMID 30497474, 2018). "Results suggested that high levels of BCL2L1 decease the survival of lung cancer patients (HR (95%CI) = 1.75(1.33~2.30)), while patients survival time was unaffected by expression of IGF1R (HR (95%CI) = 1.15(0.98~1.36))." (PMID 30497474, 2018). "IGF1R signaling has been shown to play a crucial role in the development and progression of several types of cancer, including lung cancer." (PMID 29455661, 2018). "One of these genes, BCL2L1, is known to collaborate with SOX2 to promote cell proliferation in lung cancer; nuclear translocation of IGF1R induced growth arrest and apoptosis resistance of lung cancer cells." (PMID 30497474, 2018). "Survival analysis further revealed that high expression of BCL2L1 corresponded to reduced survival of lung cancer patients (HR (95%CI) = 1.75(1.33~2.30)), while patient survival time was unaffected by expression of IGF1R (HR (95%CI) = 1.15 (0.98~1.36))." (PMID 30497474, 2018). "Insulin like growth factor 1 receptor (IGF-1R) is expressed abnormally in lung cancer and mediates malignant transformation of lung tumor cell." (PMID 29861465, 2018). "The role of IGF-1/IGF-1R signaling abnormalities in lung cancer has been extensively reviewed elsewhere." (PMID 30018981, 2018). "We recently observed that IGF1R and Src were co-activated in several lung cancer cell lines and a tissue microarray consisting of lung adenocarcinoma and squamous cell carcinoma." (PMID 29455661, 2018). "The effect of differential expression of BCL2L1 and IGF1R on survival time of lung cancer patients was also investigated." (PMID 30497474, 2018). "Abnormal IGF-1/IGF-1R signaling has been extensively studied in lung cancer that mediates oncogenesis, progression, metastasis, resistance to chemotherapy, or tyrosine kinase inhibitors (TKIs)." (PMID 30018981, 2018). "There is already evidence that mTOR and its upstream activator, IGF1R, are the direct targets of miR-99a in lung cancer, esophageal squamous cell carcinoma, acute lymphoblastic leukaemia as well as HCC." (PMID 28624790, 2017). "We concluded that IGF-1R is an independent druggable target in ALK-positive lung cancer and support the trial of combination treatment." (PMID 29066738, 2017). "We confirmed that combination ALK and IGF-1R inhibitor treatment is synergistically cytotoxic to ALK-positive lung cancer cells and that this remains the case for at least 12 days after initial exposure to crizotinib." (PMID 29066738, 2017).
lung cancer (continued). "These two results revealed insignificant curative effects of IGF-1R inhibitors in pancreatic and lung cancer treatment." (PMID 28427155, 2017). "Shuanghuang Shengbai further decreased the ratios of SP+ and CD24+IGF1R+ lung cancer stem cells (P<0.05)." (PMID 28977934, 2017). "In this study, we show that depletion of SALL4 by shRNA resulted in a decreased in cell viability and tumorigenicity of SALL4-positive lung cancer cells, which were associated with dysregulation of both EGFR and IGF1R signaling pathways." (PMID 27705911, 2016). "The second example is an application from Cancer Systems Biology: we investigate the robustness of the EGFR IGF1R pathway in lung cancer." (PMID 26482604, 2015). "Figitumumab (F) was the first humanized monoclonal antibody targeting the IGF-1R studied in lung cancer." (PMID 26793618, 2015). "There are still few studies addressing the mechanism of IGF1R activation in EGFR-TKIs resistance in lung cancer cells." (PMID 26554308, 2015). "In lung cancer, Trop2 actually attenuates IGF-1R signaling-mediated AKT expression and, thus, has the opposite effect." (PMID 26000093, 2015). "High Trop2 expression attenuates IGF-1R signaling, which suppresses lung cancer growth and malignancy." (PMID 26000093, 2015). "In contrast in lung cancer cells, IGF-1R inhibition decreased the radiation-induced Ku-DNA-binding in a p38 MAPK dependent manner supporting a role for IGF-1R signaling in NHEJ mediated DSB repair." (PMID 26546517, 2015). "Our results provide pre-clinical support for the use of LL-2003 as a dual IGF-1R and Src in the treatment of lung cancer." (PMID 26515601, 2015). "For example, the expression of IGF-1R was upregulated by miR-7, miR-486 and let-7 in human gastric cancer, lung cancer and cervical cancer." (PMID 24810113, 2014). "In lung cancer cells, IGF1R and EGFR signaling play key roles and have been suggested as major factors upstream of the PI3K/AKT pathway." (PMID 25344917, 2014). "Conversely, the tumor suppressor miR-486 directly targets the components of insulin growth factor (IGF) signaling, including IGF-1, IGF-1R, and p85a, in lung cancer." (PMID 24816813, 2014). "The oncogenic receptors in lung cancer cells, including insulin-like growth factor 1 receptor (IGF-1R), TGF-beta receptor type-1 (TGFBR1), and epidermal growth factor receptor (EGFR), are direct targets of miR-133a." (PMID 24816813, 2014). "Based on these efforts, the phosphatidylinositol-3-kinase (PI3K)/protein kinase B (AKT) pathway and the IGF1/IGF1R signaling pathway have emerged as potential determinants of radiation resistance in human lung cancer cells." (PMID 25344917, 2014). "Low levels of IGF-1R copy number gain were also shown in lung cancer, pancreatic adenocarcinoma and colon cancer." (PMID 22415797, 2012). "It has been described that IGF1R upregulation promotes cell survival and proliferation in many types of cancer, including carcinomas such as prostate, breast and lung carcinomas, and also in sarcomas." (PMID 21611203, 2011). "Beside the well known effect on apoptosis, we propose potential treatment of lung cancer and IGF1R expressing blast crisis." (PMID 21124949, 2010). "We studied the effect of klotho on IGF-1 pathway activation in A549 lung cancer cells, which express high levels of IGF-1R and show an enhanced proliferation following IGF-1 treatment." (PMID 20642846, 2010). "Moreover, lactylation of SOX9 and insulin like growth factor 1 receptor (IGF1R) also contributes to the adverse progression of lung cancer." (PMID 41373440, 2025). "In addition, HIF1α is regulated synergistically with IGF1R in lung cancer through glycolysis and glutamine metabolism, result of including cancer malignant." (PMID 40290443, 2025).